LGR5 (leucine rich repeat containing G protein-coupled receptor 5)
Diseases named in the same sentence as LGR5 in open-access papers (continued):
Sharing a sentence is not in itself a finding about the gene and the disease.
adenocarcinoma (30 papers, 2011 to 2025). A common cancer characterized by the presence of malignant glandular cells. "Ki-67 was co-expressed with only a small subset of LgR5+ cells in areas which were associated with early BE (Cdx-2 positivity was observed in serial sections) (representative example of n = 41 BE and associated adenocarcinomas) and OE-33 cells." (PMID 21345220, 2011). "Data suggest that LgR5 expression in BE and adjacent EACs is associated with clinical pathological features which may predict worse clinical outcome of related (adjacent) adenocarcinomas." (PMID 21345220, 2011). "Of these 23 adenocarcinoma samples, 18 were found to be suitable for LGR5 ISH analysis, and consistent with the previous reports we generally observed LGR5 expression in the proximal portion of the gland in adenocarcinomas of all clinical stages." (PMID 25728748, 2015). "Besides Lgr5+ cells, however, lineage tracing implicates Lgr5− populations as putative cells-of-origin of the resulting hyperplastic adenomas and adenocarcinomas in this model." (PMID 33673710, 2021). "Furthermore we noted high LGR5 expression in invading cells, with later development of a stem cell niche in adenocarcinomas of all stages." (PMID 25728748, 2015). "LGR5-mRNA was significantly differentially expressed in adenocarcinomas of the oesophagus (p = 0.007), stomach [intestinal type (p = 0.006) and diffuse type (p = 0.013)], liver [CCs (p = 0.022)], colon (p<0.001) as well as rectum (p = 0.002) compared with the matched non-neoplastic tissue." (PMID 22530031, 2012). "Reportedly, microadenoma, macroadenoma to invasive well-differentiated adenocarcinoma were rapidly observed in the gastric Lgr5+ stem cells with the double deletion of Smad4 and PTEN using Lgr5-Cre mice." (PMID 33425768, 2020). "Lgr5-EGFP-CreERT2; Ppp2r1aflox/flox mice treated with DMBA and tamoxifen formed adenocarcinoma in the small intestine and colorectal regions 36 days later." (PMID 31905853, 2019). "We therefore analyzed LGR5 ISH and Ki67, KRT20 and CD44 IHC in 23 adenocarcinomas of all stages (pT1: n = 9, pT2: n = 3, pT3: n = 7, pT4: n = 4)." (PMID 25728748, 2015). "For adenocarcinomas without BE, the results of LgR5 expression were comparable with the lower expression levels of adenocarcinomas from BE." (PMID 21345220, 2011). "In addition, consistent with a role for LGR5 in invasion, LGR5 expression is enriched in CD44hiKRT20lo cells at the invasive edge of adenocarcinomas, irrespective of stage." (PMID 33673710, 2021).
gastrointestinal tumors (9 papers, 2012 to 2025). "Overall, we found that LGR5 research initially focused on the expression pattern and function of LGR5 digestive system; subsequently LGR5 mechanism in intestinal development and digestive system tumor initiation became the hot topics." (PMID 41194856, 2025). "Using an ISCs-relevant mouse model (Lgr5+ mice) and its GI tumor surrogate (Lgr5+Apc1638N/+ mice), we investigated ISCs-specific molecular alterations after high-LET radiation exposure." (PMID 39410012, 2024). "LGR5 has been shown to be a stem cell marker in previous studies including for gastrointestinal mucosa and gastrointestinal tumors, in which LGR5 is the most promising stem cell marker." (PMID 35123536, 2022). "In recent years, the role of Lgr5 in human gastrointestinal tumor development and progression has been increasingly studied." (PMID 31417548, 2019). "Previously, we mentioned that targeting LGR5 can treat gastrointestinal tumors." (PMID 37578396, 2023). "Moreover, Lgr5 is highly expressed in different human gastrointestinal tumors originating from colon, liver, pancreas, and stomach when compared to its expression in the corresponding normal tissues." (PMID 31417548, 2019). "However, a systematic analysis of LGR5 expression in a broad range of human hepato-gastrointestinal tumours and their corresponding normal tissue was as yet missing." (PMID 22530031, 2012).
colorectal (6 papers, 2011 to 2023). "Recent studies have also shown that aberrant expression of GPCR up-regulate the expression of intestine-specific stem cell marker LGR5, causing colorectal carcinogenesis in vivo and chemo-resistance in vitro." (PMID 28350360, 2017). "However, LGR5 mRNA expression was decreased in metastatic-derived colorectal tumourspheres after oxaliplatin treatment, while it was increased in primary-derived colorectal tumourspheres." (PMID 36835258, 2023). "Furthermore, LGR5 has been reported to be a CSC surface marker of colorectal carcinogenesis and a target gene of the Wnt signaling pathway." (PMID 31500591, 2019). "This study demonstrated CEACAM6, LGR5 and Wnt pathway suppression by CD151 silencing might occur through TGFβ1 regulation, offering a comprehensive view of CD151's roles in colorectal carcinogenesis." (PMID 33767593, 2021).
colonic polyps (2 papers, 2020 to 2022). "However, to truly utilize this translational model and isolate ISCs for study of intestinal disease, further work is necessary to conclude that these GFP expressing cells are in fact LGR5+ ISCs." (PMID 35669174, 2022).
inflammation (2 papers, 2024 to 2025). Aberrant reaction of the microcirculation characterized by movement of fluid and leukocytes from the blood into extravascular tissues. "Fast-cycling Lgr5+ intestinal epithelial stem cells (IESC) appear to support colonic epithelium regeneration 32, which may result in the renew and recovery of epithelium after intestinal inflammation." (PMID 38169633, 2024).
degenerative diseases (1 paper, 2019). "Importantly, a COLXXII-containing superficial layer was re-established in the healing defect, which quickly integrated with the host cartilage, indicating that these Lgr5+ cells are candidates for cell-based therapy for cartilage and ligament trauma or associated degenerative diseases." (PMID 31522976, 2019).
digestive disease (1 paper, 2025). "As a leading journal in digestive disease research, Gastroenterology emphasizes original studies on gastrointestinal pathophysiology and treatment, reinforcing the importance of LGR5 in gastrointestinal tissues." (PMID 41194856, 2025).
LGR5 also shares sentences with these, for which no sentence is quoted: diabetes (6 papers); Barrett esophagus (4); chronic gastritis (2); colon adenocarcinoma (2); colorectal polyps (2); COVID-19 (2); fibrosis (2); hepatoblastoma (2); metastasis (2); schizophrenia (2); thyroid cancer (2); 3-M syndrome (1); Acheiropodia (1); adenocarcinoma of the prostate (1); adrenal tumours (1); alcoholic liver damage (1); ameloblastoma (1); Arthritis (1); astrocytoma (1); benign tumors (1); bile duct cancer (1); biotin deficiency (1); bipolar disorder (1); bladder cancer (1); breast melanoma (1); carcinoid syndrome (1); cataract (1); cholestasis (1); chronic atrophic gastritis (1); clear cell carcinomas (1).
A further 57 diseases each share a sentence with LGR5 in 1 paper.